GSK3B (glycogen synthase kinase 3 beta)
Diseases named in the same sentence as GSK3B in open-access papers (continued):
Sharing a sentence is not in itself a finding about the gene and the disease.
Insulin resistance (continued). "GSK-3β can be activated after phosphorylation of AKT, and AKT/GSK-3β signaling plays an important role in insulin resistance." (PMID 34966805, 2021). "Meanwhile, the phosphorylation of Akt and GSK‐3β increased significantly and resulted in the inactivation of GSK‐3β and alleviation of insulin resistance." (PMID 33650786, 2021). "Therefore, inhibition of GSK3B may have the potential to treat DM and insulin resistance." (PMID 32265717, 2020). "In order to further investigate the therapeutic effect of MNAM on insulin resistance, we examined protein expression and phosphorylation levels of IRS2, PI3K, AKT, and GSK3β, part of the hepatocyte insulin signaling pathway, by Western blot." (PMID 32280711, 2020). "Moreover, we hypothesize that galangin and pinocembrin may have a synergistic effect on the improvement of insulin resistance via Akt/mTOR signaling pathway, through distinctly upregulating the phosphorylation of IR, Akt, and GSK3β and remarkably downregulating the phosphorylation of IRS." (PMID 30420897, 2018). "Both protocols of insulin resistance abolished insulin-mediated phosphorylation of Akt and GSK3β, but only IPA treatment induced the inhibitory hyper-phosphorylation of GSK3β at Ser9 (+139 ± 10%)." (PMID 29222408, 2017). "The notion of insulin resistance was clearly presented by increased p-JNK along with reduced p-Akt and p-GSK3β in HFD mice." (PMID 29163785, 2017). "In order to explore the mechanism of DSG and 5-MOP on improving insulin resistance, we examined the protein expression on the PI3K/Akt pathway including p-Src (Tyr-416)/Src, PI3Kp85/β-actin, p-Akt (Ser473)/Akt, and p-GSK-3β (Ser9)/GSK-3β." (PMID 27656241, 2016). "However, HFD failed to induce any obvious change in the phosphorylation of GSK3β in adipose tissue, which implies that the differential phosphorylation of GSK3β may be one important factor to explain a different mechanism of insulin resistance in adipose tissue induced by NPY overexpression and HFD." (PMID 25993471, 2015). "However, in insulin resistance, Akt’s impact on GSK-3β phosphorylation weakens, increasing GSK-3β activity and inhibiting glycogen synthesis." (PMID 39761309, 2025). "Analysis indicated that the 9 hub genes (AKT1, HSP90AA1, SRC, GSK3β, VEGFR2, RHOA, ENO1, PKM, and IL-2) play roles in MF treatment by participating in signaling pathways related to prostate cancer, lipid and atherosclerosis, and insulin resistance." (PMID 40051434, 2025). "Insulin resistance may also induce and aggravate AD development by inhibiting the PI3K/Akt and Wnt signaling pathways and activating GSK3β, a crucial initiator of tau protein phosphorylation." (PMID 38818523, 2024). "Insulin resistance is characterized by less sensitive insulin receptors, reduced activity of the PI3K/AKT pathway, and enhanced activity of the GSK-3β, which is in charge of increased tau phosphorylation and augmented amyloid plaque formation, which are the main pathogenic features of CD." (PMID 38536493, 2024). "AKT agonists can effectively alleviate oxidative stress, elevated blood glucose levels, and insulin resistance, suggesting that part of the diabetes mechanism induced by microplastics might be related to AKT/GSK3β phosphorylation." (PMID 38251002, 2024). "In brain insulin resistance and neurodegeneration, the PI3K/AKT/GSK3β pathway may be involved in signal transduction." (PMID 38133370, 2023). "In this study, we optimized the composition of the Cyclocarya paliurus triterpene acid complex and found that TAC can improve PA-induced insulin resistance and up-regulate the PI3K/Akt/GSK3β signaling pathway to improve the symptoms of STZ- and high-fat-diet-induced type 2 diabetic mice." (PMID 37513373, 2023). "We first showed that candesartan and azilsartan could alleviate insulin resistance in PA-treated HepG2 cells by fully restoring the impaired insulin-stimulated phosphorylation of AKT and its downstream substrates GSK3β, AS160, FOXO1, and FOXO3." (PMID 37121975, 2023).
Insulin resistance (continued). "Recent research has shown that EC ADAM17 can cleave the insulin receptor ectodomain, leading to cellular insulin resistance, which could exacerbate insulin resistance, with the initial upregulation of ADAM17 potentially leading to further GSK3β activation." (PMID 37762417, 2023). "However, this miRNA was also examined for its role in metabolic disorders such as hepatic insulin resistance and mediation in glycogenesis by regulating the AKT/GSK3β signaling pathway." (PMID 36011329, 2022). "In the present study, KK-Ay mice showed obvious insulin resistance, increased serine phosphorylation levels of IRS-1 and tyrosine phosphorylation of GSK-3β, decreased activation of Akt and serine phosphorylation of GSK-3β, and protein expression of GLUT-2, in keeping with previous studies." (PMID 35153796, 2022). "GSK-3β is an insulin signaling regulator that plays an important negative regulatory role in diabetic insulin signaling, and its enhanced expression exacerbates T2DM insulin resistance." (PMID 32714403, 2020). "In the state of insulin resistance, IRS-1 serine phosphorylation inhibits insulin signaling by decreasing tyrosine phosphorylation, and thereby inhibits downstream effectors in insulin signal transduction, such as PI3K, Akt and GSK-3β." (PMID 31952248, 2020). "To determine whether CCRK promotes hepatic insulin resistance, we utilized CCRK KO Huh7 cells, which exhibited reduced GSK3β/mTORC1 signaling compared to the WT cells." (PMID 30523261, 2018). "Insulin failed to phosphorylate IR, PKB, and GSK3β in KK-Ay, reflecting the severe insulin resistance of these mice." (PMID 29768504, 2018). "To investigate whether galangin can get insulin resistance better, we examined the phosphorylation state of ten proteins on the Akt/mTOR signal pathway, including IR, IRS1, PTEN, Akt, GSK3α, GSK3β, TSC2, mTOR, p70S6K, and RPS6." (PMID 30420897, 2018). "To investigate whether HFD-induced hepatic insulin resistance might be prevented by TM5441, we measured proteins involved in insulin signaling, such as Akt, GSK-3β, and JNK." (PMID 29163785, 2017). "Additionally, GSK3β mediating high glucose-induced ubiquitination and proteasome degradation of IRS1 enhances insulin resistance." (PMID 25089247, 2014). "As p70S6k, mTOR, Akt, GSK-3β, and PTEN are thought to be regulated by phosphorylation; it was of interest to determine if the basal phosphorylation status of these proteins is altered with insulin resistance." (PMID 20368999, 2009). "Similarly, the basal level phosphorylation of mTOR (Ser 2448), Akt (Ser 308), GSK-3β (Ser 9), and PTEN (Ser 380/Thr 382/383) was 63.0%, 25.1%, 17.5% and 31.4% higher, respectively, with insulin resistance (P < .05)." (PMID 20368999, 2009). "Meanwhile, the KD did not normalize IDE or GSK3β levels, as insulin resistance remained untreated." (PMID 39204160, 2024). "DPH5 could promote glucose uptake and consumption of IR-HepG2 cells, accelerate glucose utilization, and improve insulin resistance and insulin sensitivity by regulating PI3K/AKT-GSK3β signaling pathway and increasing the expression of GLUT4 and GSK3β proteins." (PMID 38799166, 2024). "Moreover, SH and UA treatment upregulated the expression of IRS-1, AKT, and GLUT4, which are suppressed in insulin resistance, to a similar degree to metformin, and suppressed the expression of FoxO1, PEPCK involved in gluconeogenesis, and GSK-3β involved in glycogen metabolism." (PMID 37754257, 2023). "On the other side, klotho might induce insulin resistance in adipocytes, preventing insulin effects on promotion of GLUT4 plasma membrane translocation, and attenuating intracellular insulin signalling through main mediators, such as Akt, GSK3β, and PFKf3β." (PMID 35279809, 2022). "Nevertheless, whether SOX9 and GSK3β have reciprocal regulatory relationship, how these regulations occur, and how they participate in insulin resistance are still not clear." (PMID 35281088, 2022).
Insulin resistance (continued). "Studies have shown that when insulin resistance occurred in the hippocampus, the activity of PI3K/AKT, the main signaling molecule of the insulin signaling pathway, was decreased, which promoted the activation of GSK3β and phosphorylation of tau and promoted the pathological progression of AD." (PMID 36430894, 2022). "At the insulin-resistant state, no increase could be observed in AKT phosphorylation or GSK3β phosphorylation after insulin stimulation, indicating the successful induction of insulin resistance (lane 6 versus 5)." (PMID 31723029, 2019). "As a negative effector of the insulin signaling pathway, GSK3β is involved in insulin resistance." (PMID 31293498, 2019). "On the other hand, DOX has also been demonstrated to induce oxidative stress in skeletal muscle without altering LDH but to cause insulin resistance in muscle by downregulating IRS-1, glucose transporter type 4 (GLUT4), AMPK and glycogen synthase kinase 3 beta (GSK3β)." (PMID 27512375, 2016). "In addition, the brain insulin resistance and the attenuated insulin signaling pathway (p-IRS/ p-AKT/p-GSK-3β) were accompanied by an augmentation in GSK-3β level, which in turn may contribute in the extensive alterations of Tau phosphorylation along with changes in PP2A level." (PMID 28505155, 2017). "Additionally, the research conducted on a rat model of insulin resistance induced by a high-fat and high-sucrose diet indicated that CBG (30 mg/kg) could improve liver insulin sensitivity by heightening the phosphorylation of Akt and lessening the phosphorylation of GSK-3B." (PMID 40643519, 2025). "We have not analyzed animals for insulin-resistance, PCOS or ovarian cancer cells; it would be worth studying the potential role of miR-186-5p/Gsk3b axis in ovarian tissues." (PMID 33133155, 2020).
hepatocellular carcinoma (187 papers, 2007 to 2026). A malignant tumor that arises from hepatocytes. "Bioinformatics analysis revealed upregulation of GSK3B in hepatocellular carcinoma tissue and its potential as a diagnostic marker for poor prognosis in patients with this disease." (PMID 38814517, 2024). "According to the ROC curves, GSK3B exhibited good diagnostic potential for predicting the prognosis risk of hepatocellular carcinoma patients." (PMID 38814517, 2024). "Our previous in vitro studies have shown that the mechanisms underlying the antitumor effects of bufalin in hepatoma cells appear to be mediated by AKT/GSK3β/β-catenin/E-cadherin signaling pathways." (PMID 24581171, 2014). "Similarly, a loss of Macrod2 inhibited GSK-3β activity and activated β-catenin signaling in hepatocellular carcinoma." (PMID 36010655, 2022). "Administration of DHA or EPA could cause dephosphorylation of GSK-3β, thus contributing to β-catenin degradation and apoptosis in hepatocellular carcinoma cells." (PMID 33805447, 2021). "Thus, bufalin exhibits multiple anti-tumor effects on hepatoma cells because the mechanisms underlying bufalin action appears to mediate AKT/GSK3β/β-catenin/E-cadherin signaling and affect regulation of protein expression." (PMID 23870199, 2013). "Supporting this, isorhamnetin was shown to inhibit the PI3K/Akt/GSK3β axis in hepatocellular carcinoma." (PMID 40649280, 2025). "Overall, this study reveals that circFADS1 regulates GSK3β function, influencing the progression of hepatocellular carcinoma." (PMID 39965082, 2025). "The EIF4A3/circFADS1/GSK3β/β‐catenin axis is discovered to hold promise as a novel therapeutic target for hepatocellular carcinoma, while circFADS1 is also a significant factor in lenvatinib resistance." (PMID 39965082, 2025). "This study revealed a novel role for NUAK1, which promotes the transcriptional expression of PD-L1 by activating GSK3β/β-catenin signaling pathway, leading to immune escape of hepatocellular carcinoma." (PMID 39901136, 2025). "The inhibition of glycolysis mediated by enhanced AMPK/mTOR signaling pathway signaling inhibits the activity of glycogen synthase kinase-3 beta (GSK-3β), which can suppress the acquisition of the malignant hepatocellular carcinoma (HCC) phenotype." (PMID 38482052, 2024). "Previous studies have reported that glycogen synthase kinase inhibitors can promote GSK3β phosphorylation, induce cell senescence, and result in tumor suppression in hepatocellular carcinoma." (PMID 38976093, 2024). "GSK3B overexpression has been found to enhance the proliferative and invasive capabilities of hepatocellular carcinoma cells." (PMID 38814517, 2024). "The β-Sitosterol’s potent effects based on the GSK3B need further verify in hepatocellular carcinoma cell lines (Huh-7, HCCLM3) or liver cancer patient samples by transcriptomic analysis." (PMID 38814517, 2024). "Tspan31 promotes proliferation and motility in hepatocellular carcinoma via the AKT/GSK-3β/β-catenin pathway." (PMID 38649381, 2024). "β-Sitosterol suppressed hepatocellular carcinoma cell proliferation and invasion, and enhanced apoptosis via inhibiting GSK3B expression." (PMID 38814517, 2024). "From above all, these findings suggest that GSK3B functions as a potential drug target for β-Sitosterol in regulating biologic activities of hepatocellular carcinoma cells." (PMID 38814517, 2024). "TBRG4 promotes hepatocellular carcinoma progression by inhibiting ferroptosis through the DDX56/p-AKT/GSK3β pathway and binding to Beclin1, while its knockdown reduces tumor cell proliferation, migration, and invasion." (PMID 39315094, 2024). "Above all, our data revealed that METTL1-meditated circIPP2A2 promoted malignant behaviors in hepatocellular carcinoma by serving as a scaffold in modulating the Hornerin/PI3K/AKT/GSK3β axis." (PMID 39616161, 2024). "have reported that TTYH3 can impact EMT through GSK3‐β/β‐catenin pathway in hepatocellular carcinoma." (PMID 38827027, 2024).
hepatocellular carcinoma (continued). "Their study revealed that miR-96 plays a pivotal role in activating the PI3K/AKT/GSK-3β signaling pathway in hepatocellular carcinoma." (PMID 39156976, 2024). "Recent studies have reported the role of the TTYH3/MK5 axis in regulating GSK‐3β/β‐catenin signaling in hepatocellular carcinoma, and its involvement in bladder cancer progression through the FGFR1/H‐Ras/A‐Raf/MEK/ERK pathway." (PMID 38827027, 2024). "The therapeutic potential of targeting the PI3K/AKT/GSK-3β signaling pathway in hepatocellular carcinoma (HCC) is an area of significant interest in cancer research." (PMID 39156976, 2024). "In conclusion, our findings support that targeting GSK3B is crucial for regulating biologic activities in hepatocellular carcinoma cells by using β-Sitosterol." (PMID 38814517, 2024). "GSK-3, particularly GSK-3β, plays a crucial role in the development and progression of hepatocellular carcinoma through its regulation of the PI3K/AKT pathway and other cellular processes." (PMID 39156976, 2024). "β-Sitosterol treatment further promoted the efffects of GSK3B inhibitor on hepatocellular carcinoma cells." (PMID 38814517, 2024). "EFNA4 potentially promotes hepatocellular carcinoma invasion and migration via the GSK3β signaling pathway, and is involved in the invasion of glioma via Akt signaling." (PMID 35945523, 2022). "Slug has recently been demonstrated to be a target gene in the signalling cascade TGF-β-PI3K/Akt-GSK3β-Snail-Slug-CD147, involved in epithelial mesenchymal transition and is implicated in hepatocarcinogenesis and hepatocellular carcinoma metastasis." (PMID 36128326, 2022). "Previous research has shown that ODC1 promotes hepatocellular carcinoma (HCC) proliferation by affecting the AKT/GSK3β/β-catenin pathway." (PMID 36676934, 2022). "C-Jun transcriptionally stimulated MYH9 expression to form MYH9/GSK3B/β-catenin/JUN feedback loop regulating CSC properties in hepatocellular carcinoma." (PMID 35242279, 2022). "Inactivation of GSK3β by LiCl sensitizes both hepatoma and prostate cancer to TRAIL-induced apoptosis." (PMID 33557839, 2021). "Consistently, accumulated evidence revealed that activation of PI3K/AKT/GSK-3β pathway resulted in lung cancer progression, hepatocellular carcinoma metastasis and so on." (PMID 35111682, 2021). "Insulin-like growth factor 1 (IGF1) dramatically increased DNMT1 expression in hepatocellular carcinomas (HCCs) via Akt/GSK-3β signaling pathway activation." (PMID 34162834, 2021). "Zhou and colleagues further found DSF combined with copper (DSF/Cu2+) was reported to upregulate PD-L1 expression by suppressing PARP1/GSK3β in hepatocellular carcinoma cells and ultimately prevented CD8+ TIL infiltration." (PMID 34858816, 2021). "At the same time, SNHG5 was confirmed to play a pro-cancer role in hepatocellular carcinoma by upregulating GSK3β, activating the Wnt/β-catenin pathway and promoting EMT." (PMID 33176855, 2020). "Astragaloside IV inhibits EMT by targeting the AKT/GSK3β/β-catenin pathway, which weakens the invasion and migration of hepatocellular carcinoma cells." (PMID 32082395, 2020). "One study identified S551, T555 and S589 as GSK-3β target sites based on kinase assays and experiments in hepatoma cells, while another study reported T498, S502, S505, T506, and S510 as GSK-3β sites in ovarian cancer cells." (PMID 33383924, 2020). "Inhibition of AKT/GSK-3β/β-cateninpathway inhibited cell migration and invasion in hepatocellular carcinoma cells." (PMID 31772658, 2019). "ANXA2 was reported to prevent β-catenin phosphorylation and degradation by binding glycogen synthase kinase 3β (GSK3β) and disrupting the formation of the GSK3β/β-catenin complex in hepatocellular carcinoma cells." (PMID 31695775, 2019). "The CXCR2/CXCL5 axis was also found to enhance epithelial-mesenchymal transition of hepatocellular carcinoma cells through the activation of the PI3K/AKT/GSK-3β/Snail signaling." (PMID 29743818, 2018).